MYC (MYC proto-oncogene, bHLH transcription factor)
Diseases named in the same sentence as MYC in open-access papers (continued):
Sharing a sentence is not in itself a finding about the gene and the disease.
cancer (continued). "In several cancer cell lines, these compounds downregulated MYC expression and decreased MYC stability by increasing its phosphorylation at Thr-58, driving it to proteosome-dependent degradation." (PMID 33801599, 2021). "c-MYC is one of the key TFs and accelerators of the cell cycle which plays a role in cell proliferation and is upregulated in various cancer types." (PMID 35087404, 2021). "These indicate that BMVC binds the MYC G4 with greater affinity (Kd=36 nM) and specificity, considerably stronger than other reported G4 ligands and represses c‐MYC gene expression in cancer cells." (PMID 34138492, 2021). "Based on literature information, oncogenic states are defined as abnormal marker combinations, e.g., expression of BCL6 in combination with BCL2 and/or MYC is an aggressive cancer state." (PMID 34829885, 2021). "Oncogenic signaling of growth promoting MYC in cancer cells is dependent on a functional SUMO machinery, indicating that dynamic SUMOylation and deSUMOylation are essential for the regulation of MYC." (PMID 34503213, 2021). "As c-MYC is often overexpressed in late-stage cancer, targeting it for degradation is an attractive strategy in many settings." (PMID 34636321, 2021). "Without a strategy to target the MYC protein directly, investigation has focused on identifying the pathways that MYC requires to drive cancer growth." (PMID 34788094, 2021). "The oncogenic signature of TRIM28HIGH tumors significantly reflects the enrichment of “stemness high” cancers with targets for c-Myc (MYC Proto-Oncogene)." (PMID 33810347, 2021). "Within the network MLX and MondoA can cooperate with MYC to promote tumorigenesis in MYC amplified cancers." (PMID 34236315, 2021). "There is a wealth of data indicating that the deregulation of MYC activity occurs in many cancers and contributes to disease progression, metastatic potential, and therapeutic resistance." (PMID 34778082, 2021). "It has drug-like properties with low molecular weight, which makes it a promising lead-compound for future optimization as a potential cancer therapeutic targeting MYC G4." (PMID 33978746, 2021). "While MYC is commonly activated in many cancers, MYCN is also increasingly recognized as important oncogenic driver in a growing number of cancer entities." (PMID 34262099, 2021). "Extensive evidence in the literature supports the idea that MYC inhibitors would have a huge impact on cancer treatment." (PMID 35582389, 2021). "Elevated expression of oncogenic MYC drove stemness in these cancer types and MYC-driven glycolytic program determined tumorigenic potential, thus making MYC a likely candidate linking glycolysis and stemness." (PMID 34804950, 2021). "Specifically, the PVT1 copy number increase was found to be the critical factor for MYC, and subsequent c-Myc, elevation in MYC-driven cancers." (PMID 33499210, 2021). "Many mathematical models of the MYC/E2F/miR-17-92 network were created, estimating how overexpression of the miR-17-92 cluster affects different types of cancers." (PMID 33430425, 2021). "Bromodomain factors, LIN28B, Let7 miRs, and the MYC transcription factor form a self-stabilizing positive feedback loop that is activated in diverse cancers." (PMID 34793513, 2021). "Both NOTCH and MYC—which are downregulated by MSI knockdown—are important for cancer stem cell maintenance." (PMID 34768932, 2021). "The MYC pathway is one of the most critical contributors to the genesis of many cancers, as it plays a central role in cancer initiation and progression by reprogramming a number of cellular processes." (PMID 34315512, 2021). "MYC is frequently amplified in cancer, regulates the transcription of ~15% of all genes and is a master regulator of cell proliferation." (PMID 34762642, 2021). "Alterations in the expression level of the MYC gene are often found in the cells of various malignant tumors." (PMID 34440124, 2021).
cancer (continued). "In cancer cells, KRAS mutations have been shown to give rise to a dependency on exogenous glutamine for growth and proliferation, similar to that observed in MYC amplification." (PMID 34503295, 2021). "In cancer cells, MYC and MYCN exploit the ubiquitination pathway to stabilize aberrant oncogenic signaling and drive a wide variety of cellular processes required for carcinogenesis." (PMID 33767157, 2021). "An analysis of genes within this 8q-amplicon showed that cancers that have both RRM2B-amplified along with MYC have a distinct pattern of amplification compared to cancers that are unaltered or those that have amplifications in RRM2B or MYC only." (PMID 33868369, 2021). "This interaction is a new aspect of the inhibitor so far unexplored that sets the rationale for using this inhibitor to treat MYC-deregulated cancers." (PMID 35582389, 2021). "In this review, we will examine in more detail the effect of miRNAs, long non-coding RNAs, and circular RNAs on the expression of the MYC proto-oncogene in various types of cancer." (PMID 34440124, 2021). "It is known that c-MYC favours the biosynthesis of nucleic acids and lipids in cancer and somatic cells." (PMID 34476741, 2021). "Super-enhancers, which are large clusters of transcriptional enhancers, are exploited by cancer cells to sustain oncogenic pathway activation, such as MYC." (PMID 34298787, 2021). "The predominant mechanistic basis for employing BETi for cancer treatment is the downregulation of MYC." (PMID 34865122, 2021). "Aberrant regulation of MYC is observed in more than 50% of cancers, where this oncoprotein is overexpressed, either due to enhanced transcription of the Myc gene or to dysregulated stability of MYC protein." (PMID 33718197, 2021). "MYC is overexpressed in more than half of all tumors and therefore has been regarded as one of the most important oncogenes in cancer." (PMID 34761120, 2021). "MYC promotes metabolic reprogramming in cancer and is involved in lipogenesis by pronouncedly activating acetyl-CoA carboxylase (ACACA), fatty acid synthetase (FASN), and stearoyl-CoA desaturase (SCD)." (PMID 33791309, 2021). "c-MYC is essential for glycolysis in cancer and MYC suppression prevents mitochondrial inhibitors resistance." (PMID 34804950, 2021). "The EBV latent membrane proteins also play a role in increasing MYC expression in EBV-driven cancers." (PMID 34066504, 2021). "MYC is one of the most important oncogenic drivers, its activation being reported in a variety of cancer types and sub-types, among which are the most prevalent and aggressive of all malignancies." (PMID 34503295, 2021). "This revealed a significant positive correlation between IKKα (gene symbol: CHUK) and MYC expression in prostate-, as well as other cancer types implying a functional link between IKKα expression and c-Myc levels in humans in vivo." (PMID 33461590, 2021). "In a variety of cancers, SEs are gained near MYC to up-regulate MYC and drive oncogenic transformation." (PMID 33842482, 2021). "Four other miRNAs that control MYC expression were also found in cells of this type of cancer: miR-200b-3p, miR-182-5p, miR-182a-5p, and miR-320b." (PMID 34440124, 2021). "The oncogene MYC contributes to the genesis, drug tolerance and metastasis of many human cancers, and the G2/M checkpoint controls the cell cycle fate to precisely regulate cell proliferation and division." (PMID 34885178, 2021). "Due to the difficulty to pharmacologically target MYC, it has been considered as an “undruggable” target in cancer therapy." (PMID 33572152, 2021). "MYC-orchestrated RhoA transcription has been shown to be pivotal in cell invasion and cancer metastasis, and MYC-regulated genes are one of the major targets held responsible for the antiproliferative effects of BET inhibitors in DLBCL." (PMID 34638508, 2021). "Previous studies have revealed that MYC is required for the upregulation of mevalonate pathway in certain cancer cells." (PMID 33791309, 2021).
cancer (continued). "This gain of both PVT1 and MYC has been shown to be essential for tumourigenesis in 8q24-amplified cancer cells." (PMID 33499210, 2021). "The abnormal activation of MYC in cancer results from transcriptional overexpression and/or protein stabilization." (PMID 33801599, 2021). "In recent years, a few reports indicate that MSC regulate the progression and drug resistance of cancers through MYC signaling pathway." (PMID 34789315, 2021). "MYC is a major driver of metabolic reprogramming in cancer, where this transcription factor regulates the expression of genes involved in anabolic metabolism, cellular bioenergetics and lipid metabolism." (PMID 33718197, 2021). "Neoplastic MYC transcription factor promotes malignant phenotypes of human cancers, including cisplatin resistance, but the signaling mechanisms through which MYC increases cisplatin resistance are not fully understood." (PMID 34948122, 2021). "c-MYC is the primary oncogenic driver of cancer gene expression programs in a broad spectrum of cancer types, and is an inducer of EMT." (PMID 34988459, 2021). "MYC proto-oncogene is involved in many cell processes and in the regulation of the cell cycle, the defects of which are often found in cancer." (PMID 34680956, 2021). "Suppression of expression of this ceRNA results in reduced MYC expression and suppression of cancer cell proliferation." (PMID 34440124, 2021). "In contrast to TRIM24, the expression of TRIM28 positively correlates with MYC expression in several cancer types." (PMID 33810347, 2021). "Modulating the expression or function of the enigmatic MYC protein has demonstrated efficacy in an array of cancer types and a marked potential therapeutic index and safety profile." (PMID 34577013, 2021). "One of the major targets that continues to hold promise in BRCA and other cancers is the c-MYC oncogene, which is deregulated in up to 50% of all cancers." (PMID 34803511, 2021). "Briefly, MYC is a transcription factor that regulates the expression of a variety of genes and is one of the most prevalent oncogene found to be altered in human cancer." (PMID 34073075, 2021). "It is well established that MYC controls many metabolic pathways that become dysregulated in cancer including glycolysis and lactate production." (PMID 34556188, 2021). "MYC overexpression occurs in 30% of human cancers, including Burtkitt’s lymphoma, diffuse large cell lymphoma, multiple myeloma, and acute lymphocytic leukemia." (PMID 34199901, 2021). "Lying within this region is one of the most studied oncogenes MYC, which is estimated to be involved in 20% of human cancers." (PMID 33499210, 2021). "Translocations in MYC occur often in hematopoietic cancers, and it was reported to be the third most frequently amplified gene in human cancers in a whole-genome copy number analysis." (PMID 33858415, 2021). "Enrichment analysis of 50 cancer hallmarks and 132 immune signaling modules showed that CSF-1, MYC, TGF-β, JAK/STAT3, IFN-α, and the other 29 signaling pathways were enriched in C2 versus C1 subtype (P < 0.05)." (PMID 34722280, 2021). "TT‐seq unveiled the extent and specificity of enhancer transcription across multiple diverse cancer cells, recapitulating the MYC gene's complex cis‐regulatory architecture in great detail." (PMID 33502116, 2021). "Despite decades of intensive research, the mechanism through which MYC(N) proteins drive cancer formation remain poorly understood." (PMID 34262099, 2021). "Further analysis of CNV in 8q24.2 at genetic resolution revealed that amplifications of the oncogenes, MYC (p = 0.0001) and NDRG1 (p = 0.0004), located on this fragment were also associated with HRD in a pan-cancer manner." (PMID 34976815, 2021). "The RAS and the MYC oncogenes interplay and interdependency play an essential role in driving cancer development." (PMID 34944853, 2021).
cancer (continued). "c-MYC is one of the most frequently perturbed oncogenes in human cancers, with over 40% of tumors showing overexpression at the protein level." (PMID 33513764, 2021). "LncRNAs can be regulated by MYC in different cancer types or control MYC expression, both at the transcriptional and post-transcriptional levels." (PMID 33806217, 2021). "HIF-2α can drive cyclin D1 and cyclin D2 expression, notably through c-MYC activation for the latter, and promote cancer cell proliferation." (PMID 34539584, 2021). "In thyroid cancer, lncRNA MALAT1 competitively binds to miR-204, upregulates IGF2BP2 and enhances MYC expression in m6A-dependent manner, conferring a stimulatory effect on cancer progression." (PMID 35004679, 2021). "Through targeting of MYC dependence in cancer cells, they have shown promising efficacy in a variety of solid tumors and hematological malignancies, including DLBCL." (PMID 34638508, 2021). "Others have proposed targeting oncogenic MYC as a strategy for cancer treatment, proposing the destruction of a microtubule-bound MYC reservoir during mitosis contributes to vincristine ́s anti-cancer activity." (PMID 33909629, 2021). "It is well established that c-MYC plays a pivotal role in chemoresistance and that silencing of c-MYC enhances chemosensitivity in cancer cells." (PMID 34803511, 2021). "Recent studies show that, in malignant cells, the expression of the MYC oncogene is crucial for cancer cells to colonise organs at the expense of less performant neighbours." (PMID 33398072, 2021). "Regarding specific cancer-associated genes, the CYT-high subgroup had more CNAs, including gains in NF1, CDK12, ERBB2, RARA, MDM4 and MYC; and losses in BRCA1, CD274 and APC." (PMID 34316699, 2021). "At least one of the proteins encoded by MYC, MYCN and L-MYC, paralogous members of the MYC family, are deregulated in over 50% of human cancers." (PMID 33760847, 2021). "In contrast, FTH1 overexpression inhibited cell growth, decreased c‐MYC expression, and sensitized cancer cells to chemotherapy; silencing of c‐MYC recapitulated the effects of FTH1 overexpression." (PMID 34551213, 2021). "Inhibition of AURKA or AURKB triggers transient mitotic arrest, polyploidization, and apoptosis of MYC expressing cancer, phenotypes reminiscent of those observed here for diMF." (PMID 33760847, 2021). "LDHA is frequently upregulated in CRC and identified as a direct target gene of the c-MYC oncogenic transcription to reprogram cancer metabolism." (PMID 34887764, 2021). "One of the critical findings of our current study is that a small molecule PARP inhibitor (i.e., olaparib) suppresses the activity of neoplastic MYC transcription factor, especially in cancer cells spontaneously acquired cisplatin resistance." (PMID 34948122, 2021). "We and others have previously shown that, as in cancer cells, c-MYC induces a Warburg effect in cells undergoing reprogramming." (PMID 34476741, 2021). "By orchestrating a pro-cancer program across multiple cellular pathways, c-MYC acts as a fundamental positive regulator of MM cell growth." (PMID 34769070, 2021). "Cancer cells with overexpressed MYC show higher transcriptomic abundance than normal cells because MYC located in promoters and enhancers can directly recruit the transcriptional elongation factor P-TEFb, resulting in transcriptional amplification." (PMID 34159316, 2021). "CDK9 was involved in cancer progression through BRD4-dependent recruitment of p-TEFb involving transcription of the MYC gene, and that MYC is a proto-oncogene that controls cell growth and cell cycle processes." (PMID 35087760, 2021). "The cancer-enabling properties of the c-MYC protein come from its activity as a “master regulator” to propagate expression of multiple pathways associated with hallmarks of cancer, such as cell cycle signaling, and glycolysis and other metabolic cascades." (PMID 33513764, 2021).
cancer (continued). "MYC is also one of the most frequently altered oncogenes, being aberrantly expressed in <70% of all cancers." (PMID 34062779, 2021). "MYC is an oncogene responsible for excessive cell growth in cancer, enabling transcriptional activation of genes involved in cell cycle regulation, metabolism, and apoptosis, and is usually overexpressed in GC (Maués, 2018)." (PMID 35082831, 2021). "Furthermore, previous studies have supposed that BLM serves as a cancer suppressor through targeting the proto-oncogene c-MYC, and recent researches also proposed that a series of malignancies are associated with the overexpression of the MYC gene and loss of BLM function." (PMID 33828983, 2021). "Cluster 0 and 6 were enriched in cells expressing genes related to cell cycle and cancer-associated proliferation (SFRP2, CENPF, TOP2A, UBE2C, CRABP2, MYC)." (PMID 33771987, 2021). "In AA men, both c‐MYC oncogene expression and telomerase activity are elevated and at a level that is significantly higher than for CA men, so maintaining the cancer cells' replicative potential." (PMID 33599076, 2021). "This normal cell dependency on rapid increases in MYC levels is exploited by cancer cells through perturbations of the normal cellular mechanisms which destabilise MYC proteins." (PMID 33658627, 2021). "Previously, it was shown that c-MYC regulates mitochondrial glutaminase expression and glutamine metabolism in cancer cells." (PMID 34887764, 2021). "It seems, therefore, justified to conduct further studies on their influence on the growth and proliferation of cancer cells, with particular emphasis on the role of the MYC gene, encoding the c-MYC protein." (PMID 34371857, 2021). "The preclinical study showed that when cancer cell lines with KRAS mutations were treated with voruciclib, all cell lines had decrease in viability, and reduced MYC levels were noted." (PMID 34944853, 2021). "It has been documented that MYC promotes the resistance of various cancer cells to cisplatin, but precisely how this oncoprotein increases cisplatin resistance is unclear." (PMID 34948122, 2021). "In general, MYC is overexpressed or deregulated in many human malignancies, so neoplastic MYC activity has been suggested to be an ideal target for cancer chemotherapy." (PMID 34948122, 2021). "Nevertheless, the SUMO regulation of MYC adds another layer of complexity to the regulation of MYC protein stability and activity and provides another target in MYC-driven cancer cell growth." (PMID 34178666, 2021). "The MYCN cancer gene in the MYC family is a structurally and functionally similar fragment of MYC discovered by Schwab in 1983." (PMID 33968733, 2021). "Hyperactivation of MYC occurs in the majority of all human cancers classifying this protooncogene as a major cancer driver." (PMID 33937075, 2021). "The oncogenic addiction of cancer cells on MYC explains the increased sensitivity of cancer cells to drugs targeting MYC directly or indirectly." (PMID 34637026, 2021). "This review offers a comprehensive and specific overview of recent discoveries in the regulation of MYC oncogene activation on glutamine metabolism in cancer cells." (PMID 34503295, 2021). "We established and validated a new 3-compartment model that quantifies the expression levels of a driver oncogene such as MYC in individuals with an oncogene-addicted cancer." (PMID 33446671, 2021). "We identify an immediate early transcriptional response that is strongly dependent on HIF1A and the kinase activity of its cofactor CDK8, includes indirect repression of MYC targets, and is highly conserved across cancer types." (PMID 33654095, 2021). "From a mechanistic point of view, MYC is an essential regulator of cancer cell growth, since it orchestrates a potent pro-cancer program across multiple cellular pathways, steadily including the transcription regulation of microRNAs (miRNAs)." (PMID 34503175, 2021).